CRP (C-reactive protein)
Diseases named in the same sentence as CRP in open-access papers (continued):
Sharing a sentence is not in itself a finding about the gene and the disease.
atherosclerosis (continued). "CRP can be found in the early stage of atherosclerosis, and CRP levels are closely related to atherosclerotic plaque size and the risk of recurrence after treatment." (PMID 36463176, 2022). "Further, the beneficial effects of RYGB on markers of atherosclerosis such as brachial artery flow-mediated dilation and cIMT paralleled a decrease in C-reactive protein (CRP)." (PMID 36551255, 2022). "CRP, a marker of acute inflammation, has been considered a marker for atherosclerosis and has proven useful for predicting cardiovascular disease in the general population, as well as in patients with rheumatic disease." (PMID 35160112, 2022). "COPD is characterized by a low-grade systemic inflammation (with the release of numerous proinflammatory cytokines and CRP) which can contribute to the pathogenesis of atherosclerosis and cardiovascular disease." (PMID 35402466, 2022). "Parvimonas was positively correlated with plasma CRP in subjects with asymptomatic and symptomatic atherosclerosis in previous research." (PMID 36503487, 2022). "The resultant inflammasome releases upstream inflammatory cytokines such as IL-1β that activate inflammatory cells and produce IL-6, which stimulates the production of CRP, amplifying the inflammatory cascade and promoting atherosclerosis." (PMID 36558530, 2022). "Well-known inflammatory markers, hs-CRP and IL-6 were also upregulated during atherosclerosis progression." (PMID 36428896, 2022). "CRP has been shown to accelerate atherosclerosis by directly increasing LDL-C transcytosis across endothelial cells." (PMID 35614388, 2022). "C-reactive protein (CRP) is a classic marker of inflammation and the most reliable inflammatory marker of atherosclerosis." (PMID 35308062, 2022). "Serum CRP level is a marker that reflects the extent of atherosclerosis and is a useful predictor of ischemic cerebrovascular disease and ischemic heart disease." (PMID 35085298, 2022). "CRP is a reactive protein in the acute of inflammation phase, which can promote atherosclerosis and thrombosis." (PMID 36065806, 2022). "CRP is involved in all stages of atherosclerosis by participating in various mechanisms such as complement activation, lipid accumulation, thrombosis, and monocyte recruitment." (PMID 36553147, 2022). "In a previous study, we found that patients with SpA and persistent inflammation as defined by CRP had greater right and left cIMT, thus pointing to a link between CRP and subclinical atherosclerosis." (PMID 35160112, 2022). "CRP is closely linked to multiple cardiovascular risk factors (as well as adiposity) and therefore the relationship between CRP and cardiovascular outcome may reflect changes other than weight status or even the direct effects of semaglutide on atherosclerosis." (PMID 36467859, 2022). "Hyperuricemia can promote the development of atherosclerosis by regulating inflammatory pathways such as nod-like receptor protein 3 inflammasomes, macrophage M1/M2 polarization, and C-reactive protein." (PMID 35456221, 2022). "CRP caninduce atherosclerosis through the generation of ROS activation ofNF-κB, and increased expression of CAM, and MCP-1." (PMID 39077184, 2022). "Further, the CRP concentrations were significantly higher (P < 0.05) in HED group than those in ND group, which was potentially associated with the occurrence of atherosclerosis." (PMID 35284467, 2022). "Keywords with high centrality were adipose tissue, proteomics, artery disease, C-reactive protein, coronary artery disease, metabonomics, and atherosclerosis." (PMID 35402548, 2022). "In hypertensive individuals, CRP levels are associated with cardiovascular events and end-organ damage because CRP is correlated with vascular stiffness and severity of atherosclerosis." (PMID 36010315, 2022). "In the current study, the mean values of CRP and IL-6 were significantly elevated in obese, obese with atherosclerosis compared with control group." (PMID 36407366, 2022).
atherosclerosis (continued). "Selected factors were compared with basic laboratory parameters that are potentially related to atherosclerosis: C-reactive protein (CRP) and lipid concentration." (PMID 36360388, 2022). "At the same time, high concentrations of CRP can promote thickening of the intima and atherosclerosis, leading to remodeling of hypertensive vessels." (PMID 36418968, 2022). "The association between genetic variations in the CRP gene, estrogen use and CRP levels or preclinical signs of atherosclerosis is however not fully known." (PMID 35428187, 2022). "The Multi-Ethnic Study of Atherosclerosis (MESA) has depicted this relationship between reducing CRP and inflammatory cytokines after a fiber-rich vegetarian diet compared to a fat-rich, dietary fiber-devoid omnivore diet." (PMID 35745278, 2022). "One of the aims of the present study was to elucidate the relationship between CRP genotype and signs of early atherosclerosis in the Swedish Lifestyle, Biomarkers and Atherosclerosis (LBA) cohort, which consists of young, healthy non-smoking individuals." (PMID 35428187, 2022). "SYK plays a critical regulatory role in the inflammatory process of atherosclerosis, such as oxidized lipid deposition, C-reactive protein, NF-κB activation, platelet activation, and inflammatory body activation." (PMID 34777534, 2021). "By using proteomic analysis, we found that various pathologic signaling pathways such as LXR/RXR activation, atherosclerosis, and complement activation were upregulated in the mCRP-deposited dilated aortic walls with high serum CRP level." (PMID 34428207, 2021). "Lipidmetabolism disorders are the main factors behind the development andprogression of the atherosclerosis underlying CVD, while the C-reactive protein(CRP) is a marker of systemic inflammation." (PMID 35127146, 2021). "Its expression is regulated by the same pro-inflammatory stimuli that trigger the acute phase response and the synthesis of C-reactive protein, serum amyloid alpha, and fibrinogen, all considered as markers of vascular inflammation and atherosclerosis." (PMID 33923220, 2021). "Clinical studies report that smokers also have an increased expression of pro-inflammatory markers including IL-6, CRP, E-selectin, P-selectin, and intercellular adhesion molecule-1, all of them well-known players in the pathogenesis of atherosclerosis." (PMID 34440753, 2021). "The SDF1 ROC curve for clinical atherosclerosis manifestations was significantly improved when CRP was included in the model [AUC (95%CI): 0.70 (0.62–0.73); p = 0.005]." (PMID 34062730, 2021). "This phase 2 trial observed a decrease in CRP levels in serum upon MLN1202 treatment, pointing towards a reduced risk in the development and progression of atherosclerosis." (PMID 34501271, 2021). "In patients with atherosclerosis (and vascular inflammation generally), levels of CRP usually are very low; therefore, hs-CRP tests are used to quantify its concentration." (PMID 34356982, 2021). "Sleep fragmentation also increases inflammatory markers (IL-1, IL-6, IL-17, CRP and TNF-α) and triggers a low-grade chronic inflammatory status, hereby increasing atherosclerosis risk and severity, even independently of other atherosclerotic risk factors." (PMID 34440753, 2021). "The proinflammatory markers including oxidized LDL, proinflammatory cytokines, adhesion molecules, serum amyloid A (SAA), and C-reactive protein (CRP) play an important role in the progress of atherosclerosis." (PMID 34604350, 2021). "Previous studies have reported elevated levels of IL-6 and CRP in pathologies with low-grade inflammatory status, such as proteinuric diabetic nephropathy, or atherosclerosis and cardiovascular morbidity." (PMID 34064366, 2021). "UA triggers the expression of pro-inflammatory cytokines such as C-reactive protein, contributing to atherosclerosis." (PMID 34218791, 2021).
atherosclerosis (continued). "Some studies have also reported a decrease in Pentraxin -3 (PTX3), which is structurally related to CRP and plays a regulatory role in inflammation with a possible protective effect against atherosclerosis and cardiovascular risks." (PMID 33800490, 2021). "Our finding that the site of mCRP deposition was between atherosclerosis and the degenerated aortic wall suggests that there is a cross-talk between CRP and atherosclerosis in the pathogenesis of AAA." (PMID 34428207, 2021). "Despite CRP was excluded from the pathogenesis of inflammatory related conditions (i.e., such as atherosclerosis) by a subsequent mendelian randomization, it remains a proxy of the overall systemic inflammatory status." (PMID 34394107, 2021). "In fact, model 3, including all confounding factors, showed an OR of 2.8 (95%CI: 1.2–6.8; p = 0.022) for the combination of SDF1 and CRP with clinical atherosclerosis." (PMID 34062730, 2021). "Much is known about the relationship between CRP and obstructive coronary heart disease, CRP is not only an excellent biomarker for detecting inflammation, but is also directly involved in the pathogenesis of atherosclerosis." (PMID 34683106, 2021). "For example, elevated serum levels of CRP in the inflammatory process of atherosclerosis have been widely considered to increase intimal thickness and plaque rupture, resulting in acute cerebral infarction." (PMID 34489618, 2021). "CRP also plays a direct regulatory role in the process of atherosclerosis, which is related to cytokine release, smooth muscle cell migration, extracellular matrix remodeling, endothelial dysfunction, and the activation of circulating monocytes." (PMID 34900087, 2021). "Biomarkers derived from routine blood sampling including C-reactive protein (CRP), neutrophil-to-lymphocyte ratio (NLR), platelet-to-lymphocyte ratio (PLR) and mean platelet volume (MPV) have been associated with progressive atherosclerosis." (PMID 34341413, 2021). "In the late-stage of KD, markers of atherosclerosis such as endothelial dysfunction, oxidative stress, elevated levels of high-sensitivity C-reactive protein (hsCRP)/C-reactive protein (CRP), and inflammatory cytokines have been reported." (PMID 33937365, 2021). "On the other hand, accumulating evidence suggests that CRP levels are one of the most powerful predictors of atherosclerosis and vascular death, offering prognostic value significantly exceeding that of LDL-C." (PMID 33407555, 2021). "Major inflammatory markers of atherosclerosis are high sensitivity C-reactive protein (hs-CRP), TNFα, and IL-6." (PMID 34452133, 2021). "For example, it has been shown that trans-fatty acids potentiate the levels of inflammatory mediators, such as C-reactive protein (CRP) and interleukin (IL) 6, predisposing to atherosclerosis." (PMID 34063835, 2021). "CRP, the product and mediator of inflammatory responses in atherosclerosis, is an important marker of endothelial dysfunction." (PMID 34332541, 2021). "Of note, one of the aged NHPs under standard diet had high CRP, vascular inflammation and atherosclerosis in one location, heart inflammation and myocardial fibrosis." (PMID 33937770, 2021). "Inflammation has been recognized as a major mechanism of atherosclerotic lesion and CRP deposit formation in the arterial wall during atherosclerosis." (PMID 34876165, 2021). "The plasma concentration of CRP is relatedto the prognosis of disease progression in atherosclerosis, chronic heartfailure, atrial fibrillation, myocarditis, aortic regurgitation, and theprognosis after heart transplantation." (PMID 35127146, 2021). "In asymptomatic individuals, CRP was used as a clinical marker of inflammation with the elevated serum level being an independent predictor of cardiovascular disease, including atherosclerosis." (PMID 33564690, 2021).
atherosclerosis (continued). "Inflammation is also reported to play a pivotal role in the pathogenesis of atherosclerosis and cardiovascular disease, with c-reactive protein (CRP) emerging as inflammatory biomarker in AMI." (PMID 34332589, 2021). "Due to the fact that the inflammatory response is deeply involved in the development and progression of atherosclerosis, CRP can also be a marker for atherosclerosis." (PMID 34362075, 2021). "Interestingly, CRP was also a positive correlation between PAS in our study which may reinforce the well-known effect of inflammation in the formation of atherosclerosis, but the causal relationship between ANGLPT3, inflammation, and atherosclerosis needs further clinical studies for clarification." (PMID 34684048, 2021). "Chronic inflammation, manifested by persistently increased C reactive protein (CRP), is associated with subclinical atherosclerosis and CV-realted death." (PMID 33259776, 2021). "Inflammatory markers, including CRP, IL-6, and Pentraxin-3, are used to monitor the atherosclerosis process in coronary artery disease." (PMID 33613306, 2021). "As the main transcription factor of the inflammatory response, NF-кB can be activated by IL-6, TNF-α, CRP, and so on, which participates in the whole process of atherosclerosis." (PMID 34568579, 2021). "The role of CRP in atherosclerosis is however still under debate and cannot be compared to acute ischemic incidents regarding the circulating concentration of CRP." (PMID 33679775, 2021). "Our data also provide a proof of concept that a local inflammation-induced structural change in native CRP is a prerequisite for CRP to control the development of atherosclerosis." (PMID 32849641, 2020). "Aldosterone regulates the initiation and development of atherosclerosis which is identified as a chronic inflammatory disease by promoting the generation of C-reactive protein in vascular smooth muscle cells." (PMID 32831861, 2020). "While, after three months, the CRP levels were higher in atherosclerosis than in other etiologies (cardioembolic: 2.66 (1.07–5.46); atherosclerosis: 3.48 (1.42–9.99); lacunar: 2.65 (1.26–4.82))." (PMID 33050269, 2020). "Markers of premature atherosclerosis, such as C-reactive protein (CRP), homocysteine and endothelial dysfunction were shown to be involved in CIMT increase." (PMID 32330202, 2020). "The Multi-Ethnic Study of Atherosclerosis revealed that higher IL-6 and CRP concentrations indicate a faster declining rate of kidney function." (PMID 32877465, 2020). "In prior research, we have shown that inflammatory markers such as hs-CRP levels were independent predictors of baseline and progression of atherosclerosis as measured by carotid IMT in HIV-infected adults." (PMID 32353062, 2020). "Our major finding was that the administration of mutant CRP for 7 weeks slowed the progression of atherosclerosis." (PMID 32849641, 2020). "In atherosclerosis, different proteins activate different complement pathways: C-Reactive Protein (CRP) bound to ligands, immune complexes, enzyme-modified low-density lipoproteins, apoptotic substances, and phospholipids." (PMID 33250683, 2020). "Accumulation of macrophages at the site of endothelial injury regulate the endothelin A receptors shift to endothelin B receptors and enhance endothelin system, and further express C-reactive protein (CRP) mRNA contribute to the progression of atherosclerosis." (PMID 32214403, 2020). "These six genes are involved in the development of atherosclerosis, including CRP, endothelin receptor type A (EDNRA), PON 1, fibrinogen alpha chain (FGA), fibrinogen beta chain (FGB), and fibrinogen gamma chain (FGG)." (PMID 32214403, 2020). "It starts with the deposition of CRP in the local area of atherosclerosis, which induces endothelial cells to secrete and express adhesion molecules and chemokines, promotes macrophages to express cytokines and tissue factors and stimulates the uptake of LDL." (PMID 32355581, 2020).
atherosclerosis (continued). "Recently, it has been revealed that many inflammatory markers, such as CRP, platelet/lymphocyte ratio (PLR) and neutrophil/lymphocyte ratio (NLR), WBC, TNF-α, and cytokines can be independent risk factors for atherosclerosis." (PMID 33134969, 2020). "The damage-associated molecular pattern molecule CRP and S100A9 are important factors in the inflammatory process of atherosclerosis." (PMID 33167400, 2020). "Increased serum CRP levels are independently determinative for elevated mortality and poor clinical outcome in elderly patients with vascular diseases such as atherosclerosis, coronary heart disease and stroke." (PMID 32399347, 2020). "The previous study has also shown that CRP has a higher expression level in atherosclerosis patients." (PMID 32358950, 2020). "Based on the data obtained from a single regimen for mutant CRP treatment, we conclude that one of the functions of CRP is to confer protection against atherosclerosis." (PMID 32849641, 2020). "An appropriate inflammatory microenvironment at the site of LDL deposition seems to be critical for CRP to prevent atherosclerosis." (PMID 32849641, 2020). "Based on previous studies it also appeared that cumulative effect of serum LDL levels and plasma CRP indicated important implications on atherosclerosis." (PMID 32428019, 2020). "FCGR2A serves an essential role in atherosclerosis by combining with CRP, which leads to increased secretion of inflammatory cytokines, chemokines, and ROS." (PMID 32684073, 2020). "It has been demonstrated that CRP is localized in atherosclerotic lesions to modulate the pathogenesis of atherosclerosis." (PMID 32358950, 2020). "The co-localization of CRP and low-density lipoproteins (LDL) at atherosclerotic lesions suggests a possible role of CRP in atherosclerosis." (PMID 32849641, 2020). "The role of systemic inflammation and, consequently, of high levels of CRP has been described in all phases of atherosclerosis, from the onset and build-up of plaque to rupture." (PMID 31939522, 2020). "This is an important observation, as CRP is involved in the progression of atherosclerosis at every stage of its development, as well as contributes to CVD risk." (PMID 32670417, 2020). "In consideration of the important role that inflammatory processes play in the physiopathology of CVD and atherosclerosis, CRP, as an inflammatory biomarker, had been suggested to be a marker for atherosclerosis and cardiovascular risk prediction." (PMID 33204538, 2020). "Atherosclerosis is an inflammatory cardiovascular disease and CRP is a plasma protein produced by the liver in inflammatory states." (PMID 32849641, 2020). "In atherosclerosis-related experiments in mice, CRP bound to the Fc receptor CD32, while mCRP bound to another human Fc receptor subtype CD16 in neutrophils and performed function that was opposite to that of CRP." (PMID 33008437, 2020). "Previous studies have investigated the role of inflammatory mediators, cytokines, and some vasoactive substances as important risk factors of atherosclerosis, including TNF-α, IL-1, IL-6, IFN-γ, and C-reactive protein (CRP)." (PMID 32489565, 2020). "However, low-doses of MTX do not reduce inflammatory factor levels (e.g., interleukin-1β, interleukin-6, or C-reactive protein) and the risk of ASCVD among patients with stable atherosclerosis." (PMID 32576189, 2020). "Inflammation plays a central role in the pathogenesis of atherosclerosis; elevated levels of C-reactive protein (CRP), interleukin-6, and N-terminal pro-hormone B-type natriuretic peptide (NTproBNP) correlate closely with cardiac events." (PMID 33390933, 2020). "The aim of this study was to investigate the effect of pentameric CRP (pCRP) and monomeric CRP (mCRP) on the production of atherosclerosis-related factors in cultured human coronary artery endothelial cells (HCAECs)." (PMID 32358950, 2020). "Administration of mutant CRP into mice every other day for a few weeks slowed the progression of atherosclerosis." (PMID 32849641, 2020).